H1-8 (H1.8 linker histone)
Description:
May play a key role in the control of gene expression during oogenesis and early embryogenesis, presumably through the perturbation of chromatin structure. Essential for meiotic maturation of germinal vesicle-stage oocytes. The somatic type linker histone H1c is rapidly replaced by H1oo in a donor nucleus transplanted into an oocyte. The greater mobility of H1oo as compared to H1c may contribute to this rapid replacement and increased instability of the embryonic chromatin structure. The rapid replacement of H1c with H1oo may play an important role in nuclear remodeling (By similarity).
Synonyms: osH1; H1FOO; H1OO; H1.8
Tractability: No criterion of Open Targets' tractability assessment is met for any kind of drug.
Gene: Protein-coding gene on chromosome 3 (129,543,175 to 129,551,467, forward strand). Ensembl gene ENSG00000178804.
Subcellular location: Cytoplasm; Nucleus; Chromosome
Pathways (Reactome):
Developmental Biology: Replacement of protamines by nucleosomes in the male pronucleus
Gene Ontology:
Molecular function: double-stranded DNA binding; nucleosomal DNA binding; structural constituent of chromatin; DNA binding
Biological process: chromosome condensation; epigenetic regulation of gene expression; negative regulation of DNA recombination; nucleosome assembly
Cellular component: extracellular exosome; nucleolus; nucleus; chromosome; cytoplasm; nucleosome
Genetic constraint (gnomAD): Loss-of-function variants: 13 observed, 19.11 expected, observed/expected ratio (o/e) 0.68, 90% interval 0.44 to 1.08. The upper end of that interval is the gene's LOEUF score, 1.08, which puts it in group 4 of 6, group 1 being the genes least tolerant of losing a copy. Missense variants: 432 observed, 446.89 expected, observed/expected ratio (o/e) 0.97, 90% interval 0.89 to 1.05. Synonymous variants: 193 observed, 174.32 expected, observed/expected ratio (o/e) 1.11, 90% interval 0.98 to 1.25.
Homologues: Orthologues: chimpanzee H1-8 (99% identical), macaque H1-8 (89% identical), dog H1-8 (57% identical), pig H1-8 (51% identical), mouse H1f8 (42% identical), rat H1f8 (38% identical), tropical clawed frog h1-8 (26% identical), zebrafish h1m (20% identical), Caenorhabditis elegans hil-2 (12% identical), Caenorhabditis elegans hil-3 (11% identical), Caenorhabditis elegans hil-4 (11% identical), Caenorhabditis elegans hil-6 (11% identical), and 1 more. Paralogues in human: H1-4 (22% identical), H1-5 (22% identical), H1-2 (21% identical), H1-3 (21% identical), H1-1 (18% identical), H1-0 (17% identical), H1-6 (16% identical), H1-10 (12% identical), H1-7 (11% identical).
Diseases named in the same sentence as H1-8 in open-access papers:
H1-8 is named in the same sentence as 2 diseases in open-access papers, as found by Europe PMC text mining. Sharing a sentence is not in itself a finding about the gene and the disease. The quoted sentences say what the papers report.
skin infection (1 paper, 2024). An inflammatory process affecting the skin, caused by bacteria, viruses, parasites, or fungi. "The catabolism of h18:0 was >10-fold lower in bone marrow-derived macrophages isolated from Ppara−/− knockout mice, and we recover 74-fold fewer S. aureus cells from the skin infection site of Ppara−/− knockout mice compared to wildtype mice." (PMID 38601738, 2024).
H1-8 also shares sentences with these, for which no sentence is quoted: schizophrenia (1 paper).